DCAF10 (DDB1 and CUL4 associated factor 10)
Description:
May function as a substrate receptor for CUL4-DDB1 E3 ubiquitin-protein ligase complex.
Synonyms: WDR32; MGC10765; FLJ23201
Tractability: PROTAC: ubiquitination databases record sites on it.
Gene: Protein-coding gene on chromosome 9 (37,800,554 to 37,867,666, forward strand). Ensembl gene ENSG00000122741.
Subcellular location (Human Protein Atlas): Nucleoli fibrillar center
Pathways (Reactome):
Metabolism of proteins: Neddylation
Gene Ontology:
Molecular function: protein binding
Biological process: regulation of apoptotic process; protein ubiquitination
Cellular component: Cul4-RING E3 ubiquitin ligase complex; Cul4A-RING E3 ubiquitin ligase complex; Cul4B-RING E3 ubiquitin ligase complex; nucleoplasm
Genetic constraint (gnomAD): Loss-of-function variants: 18 observed, 40.2 expected, observed/expected ratio (o/e) 0.45, 90% interval 0.31 to 0.66. The upper end of that interval is the gene's LOEUF score, 0.66, which puts it in group 2 of 6, group 1 being the genes least tolerant of losing a copy. Missense variants: 497 observed, 655.81 expected, observed/expected ratio (o/e) 0.76, 90% interval 0.7 to 0.82. Synonymous variants: 288 observed, 261.26 expected, observed/expected ratio (o/e) 1.1, 90% interval 1 to 1.22.
Homologues: Orthologues: chimpanzee DCAF10 (99% identical), macaque DCAF10 (98% identical), dog DCAF10 (93% identical), pig DCAF10 (91% identical), rabbit DCAF10 (91% identical), mouse Dcaf10 (89% identical), rat Dcaf10 (89% identical), guinea pig DCAF10 (88% identical), tropical clawed frog dcaf10 (70% identical), zebrafish wdr32 (64% identical), Drosophila melanogaster CG1523 (30% identical).
Diseases named in the same sentence as DCAF10 in open-access papers:
DCAF10 is named in the same sentence as 4 diseases in open-access papers, as found by Europe PMC text mining. Sharing a sentence is not in itself a finding about the gene and the disease. The quoted sentences say what the papers report.
colorectal cancer (1 paper, 2026). A primary or metastatic malignant neoplasm that affects the colon or rectum. "In DLD-1 (colorectal cancer) and RPE-1 (non-transformed, near-diploid retinal pigment epithelium), co-depletion of DCAF10 with NMT1/2 increased Lyn, Fyn, and Src relative to NMT1/2 knockdown (KD) alone." (PMID 41484149, 2026).
lung adenocarcinoma (1 paper, 2026). A carcinoma that arises from the lung and is characterized by the presence of malignant glandular epithelial cells. "DCAF10 is insufficiently studied, yet its high expression correlates with better ovarian cancer survival, while its loss predicts poor lung adenocarcinoma prognosis, suggesting a protective role." (PMID 41484149, 2026).
tumor (2 papers, 2021 to 2025). "However, the depletion of DCAF10 rescued the tumor suppression of ectopic OTUD1 expression in K244R mutant cells (comparing K244R&D1&shDCAF10 to K244R&D1), which is due to the inhibition of the MCL1 downregulation‐induced caspase‐dependent apoptosis pathway and AIF release (parthanatos)." (PMID 33898171, 2021).
DCAF10 also shares sentences with these, for which no sentence is quoted: ovarian carcinoma (1 paper).